CHEK2 (checkpoint kinase 2)
Diseases named in the same sentence as CHEK2 in open-access papers (continued):
Sharing a sentence is not in itself a finding about the gene and the disease.
tumor (continued). "The two other variants indicated CHEK2 carrier ship; there was no indication of biallelic CHEK2 loss in the tumor, and probably, these tumors originated independently of the CHEK2 germline variant." (PMID 35053600, 2022). "Most CHEK2-associated tumours were classified as ccRCCs [19 ccRCC, five non-ccRCC (n = 4 chRCC, n = 1 oncocytic) and n = 3 histology not available]." (PMID 35441217, 2022). "Variants in the CHEK2, BRCA2 and ATM tumor suppressor genes, as well as the ASXL1 and EZH2 Epigenetic Regulators, may support the self-renewal of the proliferating progenitors." (PMID 35896598, 2022). "However, as candidate tumor suppressor, CHEK2 contributes to molecular pathogenesis in various human malignancy." (PMID 34630562, 2021). "Hence, the expression of CCNB1, CDC25C, and CHEK2 played an important role in the carcinogenicity and tumor progression of NSCLC." (PMID 34504528, 2021). "Increased loss of chromosome 22q that encodes NF2, CHEK2, and SMARCB121 were observed in type 2 PRCC, which may implicate in carcinogenesis and tumor progression." (PMID 34489456, 2021). "Furthermore, deficiencies in CHEK2, FANCC, or NBN have been shown to induce PARPi sensitivity in other tumor models." (PMID 33339368, 2020). "CHEK2 and DACH1 is a tumour suppressor, however amplification of its mutated form may cause dominant-negative effect." (PMID 31041889, 2019). "Like BRCA2- and CHEK2-associated tumours, ATM-associated tumours are mostly luminal tumours but they do not show a particular histological subtype as observed in BRCA1- (medullary), BRCA2- (lobular), CDH1- (lobular), and PTEN-associated tumours (apocrine)." (PMID 29665859, 2018). "Mechanistically, these mutations tend to disrupt the original protein function, exemplified by the disrupted substrate binding in CREBBP and EP300, or to prevent the activation of a tumor suppressor, exemplified by mutations within the SMAD4 interface or CHEK2 activation loop (Dataset EV5)." (PMID 29572294, 2018). "CHEK2 is a tumor suppressor that regulates genome stability." (PMID 26318585, 2015). "In addition, it has been shown that DNA damage-induced activation of the checkpoint kinase 2 (CHK2) results in rapid release of survivin from the mitochondria and consequently inhibition of cell death, helping to promote tumor cell survival." (PMID 24531137, 2014). "Its downregulation could be seen as a consequence of reduced CHEK2 activity, but at the same time, as a survival mechanism of the tumor cells." (PMID 21542898, 2011). "The CHEK2 gene might be a factor contributing to individual tumour development in families that are subsequently recognised as having a Li-Fraumeni phenotype." (PMID 19338683, 2009). "CHEK2 has been suggested to be a candidate tumour suppressor gene on the basis of the findings that normal function of CHEK2 is involved in DNA-damage respond and some of the mutations identified in Li–Fraumeni families were expected to result in a truncated protein." (PMID 14612911, 2003).
tumor (continued). "Genes such as BRCA1, CHEK2, and IKBKE are significantly upregulated in tumor tissues and serve as prognostic risk factors for GBM patients, suggesting that these genes may promote the initiation and progression of GBM by promoting neoplastic cell multiplication and impeding programed cell death." (PMID 41497799, 2025). "Finally, cell-derived tumor xenograft was used to evaluate the role of CHEK2 knockout in vivo." (PMID 38242891, 2024). "Increased insight into this mechanism could explain the shorter survival of CHEK2 mutation carriers that is likely driven by intrinsic tumor aggressiveness rather than endocrine resistance." (PMID 37161532, 2023). "These variants were predominantly specific to individual tumours, except for missense mutations detected in PALB2 (c.1651T>A; p.Tyr551Asn) and in CHEK2 (c.1261A>C; p.Thr421Pro), which were observed in 13 and 130 specimens, respectively, resulting in a high mutation burden, particularly for CHEK2." (PMID 37373225, 2023). "CHEK2 is not necessary for viability in animal models but increases tumor incidence, suggesting that even partial loss of expression may impair cellular response to DNA damage." (PMID 36980535, 2023). "In addition, the CHEK2 gene showed significantly higher mutation rates in patients with no triple-negative BC versus patients with a triple-negative BC tumor phenotype (3.3% vs. 0.8%, p-value = 0.002)." (PMID 38476463, 2023). "Similarly, the proportion of variants that were present on tumor testing only varied widely by gene, with the highest proportion found in RAD51C (100%, N = 2) and CDH1 (90%, N = 9) and the lowest proportion found in CHEK2 (0%, N = 0)." (PMID 35962742, 2023). "Additionally, PTTG1 may correlate with the BLCA tumor microenvironment and exert transcriptional activity by targeting CHEK2, OCIAD2, UBE2L3, and ZNF367 in BLCA tissue." (PMID 35768832, 2022). "Due to the low number of BOT patients, there remains the possibility that CHEK2 c.470T>C variant may not be directly related to tumor development, but rather may be a coincidental finding." (PMID 35313928, 2022). "However, IHC staining revealed that CHEK2 was overexpressed in tumor tissues." (PMID 35300428, 2022). "Moreover, CHEK2 p.R137* (AF 49.36%) was also detected in the tumor tissue." (PMID 35281821, 2022). "Finally, they present ed a correlation between CHEK2 mutations and the risk of recurrence but not with tumor grade." (PMID 34499690, 2021). "Thus, it appears that heterozygous loss of multiple genes residing in chromosome 22, including tumor suppressors, such as CHEK2, LZTR1 and SMARCB1, confers no proliferative advantage to the cells." (PMID 32724039, 2020). "Therefore, stromal fibroblast CHEK2 might constitute a valid therapeutic target to stop tumor progression and/or recurrence." (PMID 27484185, 2016). "Yet the finding that one of our non-functional CHEK2 mutations associated with chemoresistance (1368InsA) occurred as a somatic, not germline mutation, suggest such mutations may be selected for during tumor progression." (PMID 18725978, 2008).
tumor (continued). "The top five differential genes in LumB tumours, ranked by significance, are MIS18A, WIF1, CHEK2, EMCN and CDK4." (PMID 38332687, 2024). "If tumour genetic testing was performed, the panellists considered further germline testing appropriate in patients with high-volume mHSPC (CHAARTED criteria) having a BRCA1/2 tumour (L)PV or a non-BRCA1/2 tumour (L)PV (eg, ATM, CHEK2)." (PMID 36874601, 2023). "Given that publicly available GBM scRNA-seq datasets show heterogeneous expression of STING in tumor cells across patients, how STING promoter methylation relates to activation of STING pathway when CHEK2 is lost, remains to be determined." (PMID 36949040, 2023). "Tumor cells (HeLa and SiHa) also exhibit reduced colony formation and anchorage-independent growth potential upon ATM and CHEK2 silencing when compared to cells expressing only scrambled shRNA." (PMID 35745491, 2022). "On the other hand, CHEK2 and ATM carriers primarily develop ER-positive BCs, and the proportion of ER-positive tumours increases with age." (PMID 36162851, 2022). "Those events overlap with many characteristic breast tumor suppressor genes such as BRCA1, BRCA2, CHEK2 with inferred CN lower than basal ploidy." (PMID 35681161, 2022). "Growth curves indicate that the tumor-derived cell lines expressing different shRNAs against ATM and CHEK2 had their proliferation potential dramatically reduced, but that silencing of these genes did not affect the proliferation of PHK." (PMID 35745491, 2022). "Chromosome 22q contains several known tumor suppressors, such as NF2, CHEK2 and SMARCB1, and all the three tumor suppressors were deleted in the three cases." (PMID 28177878, 2017). "Downregulation of a new miR-17/20 target, checkpoint kinase 2 (Chek2), increases the recruitment of HuR to c-MYC transcripts, resulting in the inhibition of c-MYC translation and thus interfering with in vivo tumor growth." (PMID 26555894, 2015). "It remains uncertain whether this reflects two different tumor groups, i.e. one with complete loss of wild type CHEK2 and thereby CHEK2 driven tumorigenesis and one without thereby representing sporadic tumors, or that loss of one CHEK2 allele is sufficient to drive tumorigenesis." (PMID 26553136, 2015). "Besides, we also validated the expression levels of LM.Sig using IHC staining, and the results indicated that the expression levels of CHEK2 and GFM1 were downregulated in normal lung tissues compared to tumor tissues." (PMID 40568577, 2025). "Across several cohort studies, CHEK2 expression was negatively correlated with the efficacy of immune checkpoint inhibitors (ICI), which target the interaction between effector immune and tumor cells." (PMID 40492861, 2025).
tumor (continued). "There was a notable divergence in gene expression levels between neoplastic and neighboring tissues, with genes such as BRCA1, CHEK2, and IKBKE substantially amplified in tumor tissues, while genes such as ZMYND11, MAPK8, and RPS3 exhibited notable elevation in adjacent nontumor tissues." (PMID 41497799, 2025). "CHEK2* BCs were most similar to ER+ BCs, even indistinguishable in some aspects, suggesting overlapping tumor evolution." (PMID 37161532, 2023). "Consistent with the INPP4B tumor suppressor function, the tumorigenic markers MAPK, SRC, and SNAI2 were elevated, and the tumor suppressor proteins RB1, BRCA1, and CHEK2 were decreased in the cells treated with siRNA targeting INPP4B." (PMID 38001678, 2023). "ScRNA-seq analysis of GBM samples in two independent datasets showed negative correlation between tumor intrinsic Chek2 expression and type I interferon response and antigen presentation on tumor cells." (PMID 36949040, 2023). "All objective responses in this trial were in tumours harbouring BRCA2, ATM or CHEK2 alterations." (PMID 37365284, 2023). "The PTVs in BRCA2, CHEK2, and PALB2 were associated with larger tumor size, lymph node involvement, and higher stage at diagnosis (eFigure 1 in Supplement 1)." (PMID 35084436, 2022). "On the other hand, Checkpoint Kinase 2, codified by the CHEK2 (22q12.1) gene, acts as a tumor-suppressor in BC where gene loss is not infrequent." (PMID 36010918, 2022). "Among those with ER-negative tumours, most tumours are TN for PV carriers in all genes, except CHEK2 carriers, in whom the majority are ER-negative but not TN." (PMID 36162851, 2022). "Though in PPGLs, the function of CHEK2 gene has not been well characterized; however, CHEK2 role in cell proliferation and tumor suppression has been confirmed by various reports." (PMID 34630562, 2021). "Moreover, the CHEK2 gene is HRR-related and was altered in one tumour (with a concomitant BRCA1 alteration)." (PMID 34680387, 2021). "In vitro and in vivo (on patient-derived xenograft mice models) studies revealed an extensive activity of the other potent CHEK1 (and CHEK2) inhibitor prexasertib in HGSOC, both as a monotherapy and in combination with PARPi olaparib, with anti-tumor activity even in olaparib-resistant models." (PMID 32605254, 2020). "Both, ATM and CHEK2, were negatively associated with triple‐negative breast cancer (TNBC) and estrogen receptor (ER)‐negative tumor phenotypes." (PMID 29522266, 2018). "Furthermore, they also did not activate the other key DNA damage response protein, such as downstream target checkpoint kinase 2 (CHK2), in HCT116 and SW480 tumor cells during their induction of apoptosis and senescence." (PMID 29732005, 2018). "The present data showed also that in addition to its autonomous tumor suppressor function, CHEK2 has also a non-cell-autonomous tumor suppressor activity." (PMID 27484185, 2016).
tumor (continued). "We have shown that CHEK2 inhibits the procarcinogenic effects of breast stromal fibroblasts and has a non-cell-autonomous tumor suppressive function through repressing the expression/secretion of SDF-1 and IL-6." (PMID 27484185, 2016). "High expression of Chek1, Chek2 and MCM3 has previously been demonstrated to be associated with a poor prognosis in the here studied cohort of tumours, although not independent of other established clinicopathological parameters." (PMID 22284433, 2012). "Although it appears that much of CHEK2’s immunomodulating capabilities arise from its role in the DDR pathway, new evidence suggests that CHEK2 may play a novel role in directly altering the immune tumor microenvironment." (PMID 40492861, 2025). "Here, immunohistochemical analysis revealed that tumor tissues had higher CHK2 protein levels compared to the adjacent normal tissues, regardless of the CHEK2 mutation status of the patients, which appears to be a mechanism of the cells to signalize a defect in the DNA damage response pathway." (PMID 38367672, 2024). "Unlike CHEK2, the T-cell compartment associated with the low CHEK1 expressing tumor cells showed no significant enrichment for “Interferon γ (IFN-γ) signaling” (p = 0.76) and “T-cell-mediated cytotoxicity pathway” (p = 0.18) as compared to the T cells from high CHEK1 expressing tumor cells." (PMID 36949040, 2023). "CHEK2 BC genomes were most similar to non-HRD, ER+ BC genomes in terms of TMB, ID ratio as well as the various mutational signatures, yet they display a worse prognosis likely originating from an increased intrinsic tumor aggressiveness." (PMID 37161532, 2023). "Nine cases with germline variants in HR-related genes PALB2, BRCA1, RAD51C, FAN1 and CHEK2 also showed evidence of enrichment of the germline variant in the tumor, while the other 12 cases with HR-related gene variants (seven FAN1, three CHEK2, one BRIP1, one NBN) did not." (PMID 33917078, 2021). "Here the CHEK2 gene was overexpressed (not enough tissue to examine protein expression), and the Chk1 (checkpoint kinase 1) protein, encoded by the CHEK1 gene increased its staining from below 5% to 50% of the tumour cells after resistance." (PMID 22905093, 2012). "However, some studies have found BRCA2-associated tumours to be negative for HER2 and to over-express CHEK2 (checkpoint kinase 2) and RAD51 (homolog of Saccharomyces cerevisiae Rad51)." (PMID 18275599, 2008). "Importantly, BC arising in CHEK2, NBN/NBS1 and BLM heterozygotes usually demonstrates retention of the wild-type allele in the tumor, therefore there is no ground to expect selective chemosensitivity in these tumor types." (PMID 27555886, 2016).